MDM2 (MDM2 proto-oncogene)
Diseases named in the same sentence as MDM2 in open-access papers (continued):
Sharing a sentence is not in itself a finding about the gene and the disease.
tumor (continued). "It is reasonable to assume that in the present tumor both MDM2 amplification and the fusion genes PTGES3-PTPRB, HMGA2-DYRK2, TMBIM4-MSRB3 and USP15-CNTN1 are located on the ring chromosome although lack of suitable material prevented us from determining this with certainty." (PMID 25176350, 2014). "Phospho-MDM2, which when phosphorylated by Akt enhances cell survival, was slightly increased in WT mice, but remained relatively unchanged in the Akt knockout mice with the exception of a slight decrease in Akt3−/− mice in advanced neoplasms." (PMID 24722238, 2014). "MDM2 was found amplified in both the primary tumor and a metastasis." (PMID 25176350, 2014). "Several of the genes differentially regulated are associated with tumor initiation (e.g., AhR, CYP1A1, CYP1A2, MDM2, EGR1, NFKBIZ), further suggesting that genomic outcomes of short-term exposure truly reflect the longer-term process of malignant transformation." (PMID 25058030, 2014). "In the primary tumor, the copy number of MDM2 was 17.2 whereas the copy number of CDK4 was 2.2." (PMID 25176350, 2014). "Misregulation of MDM2 could play a role in hyperplasia and other liver remodeling processes by over-inhibiting tumor suppressors and apoptotic pathways and decreasing control of the cell cycle." (PMID 24979717, 2014).
tumor (continued). "A recent study showed that miR-17-3p reduces tumor growth by targeting MDM2 in glioblastoma cells." (PMID 25302307, 2014). "However, it is believed that MDM2 has tumor suppressor functions by inducing cell cycle arrest or targeting Slug, a key transcriptional regulator in the EMT progression for proteolytic degradation." (PMID 25149542, 2014). "Furthermore, expression of an I3C-resistant form of elastase, the only known target protein for I3C, prevented I3C anti-proliferative responses in cells and in tumor xenografts in vivo, as well as disrupting the I3C-stimulated nucleostemin–MDM2 interactions." (PMID 25209720, 2014). "As a first step towards optimizing the clinical utility of MDM2 inhibitors, we screened an 1169-compound library for agents that might synergize with MDM2 inhibition in the suppression of tumor cell viability." (PMID 24810962, 2014). "Also, Mdm2 involvement in promoting tumor angiogenesis and inflammation has recently emerged through its implication in vascular endothelial growth factor-A (VEGF-A) proangiogenic and NF-κB proinflammatory signaling." (PMID 24303114, 2013).
tumor (continued). "The use of this MDM2 inhibitor could offer a novel therapy for the treatment of GBM patients by inhibiting tumor growth." (PMID 23977270, 2013). "Although the mechanism by which MDM2 contributes to tumor initiation has been clarified with the identification of multiple interacting proteins, the precise roles of MDM2 in tumor invasion and metastasis remain unknown." (PMID 24236052, 2013). "MDM2 amplification frequency was analyzed in 22 RMS tumor samples by differential PCR." (PMID 22550420, 2012). "p14ARF is a tumor suppressor and the negative regulator of MDM2." (PMID 23226679, 2012). "In addition, previous studies showed that MDM2 overexpression occurs more frequently in metastatic and recurrent cancers than in primary tumours." (PMID 23251530, 2012). "Our results that loss of one or two alleles of Arf did not rescue the delay in tumor development caused by Mdm2 haploinsufficiency support and extend these previous findings to tumor development." (PMID 23029416, 2012). "Indeed, converging evidence supports the remarkable possibility that Mdm2 has a tumor-suppressing function within the appropriate context." (PMID 22679490, 2012).
tumor (continued). "These ubiquitin-like modifications might be priming events of the tumour suppressor functions of CK1α, when this it is freed from MDM2 interaction." (PMID 22916255, 2012). "Mdm2 heterozygosity also significantly altered tumor spectrum in some of the genotypes of mice." (PMID 23029416, 2012). "Thus, MDM2 controls processes like growth arrest, apoptosis and senescence, and MDM2 gene amplification and enhanced translation have been observed in many tumour forms." (PMID 22558411, 2012). "Under most conditions ARF functions as a tumor suppressor by binding and inhibiting Mdm2 activity." (PMID 23208375, 2012). "Indeed, MDM2 inhibitor synergizes with platinum drugs leading to 50% tumor free survival in PDAC xenograft model." (PMID 21623005, 2011).
tumor (continued). "Moreover, a significant decreased MDM2 expression is observed in those patients with advanced tumor stage and lower 3-year survival." (PMID 23724261, 2011). "In the present study, comparison of mean age of tumor diagnosis between affected carriers with different MDM2 SNP309 genotypes revealed a significant difference, but the genotype did not significantly affect the hazard for cancer development among all carriers." (PMID 20520810, 2010). "In this regard, HIPK2 is often inactivated in tumors by multiple mechanism such as gene downregulation, gene mutation, protein mislocalization as well as by protein degradation through MDM2 or hypoxia-induced factors, impairing the cellular response to drug and supporting tumor progression." (PMID 19828042, 2009). "MDM2 was initially found as a product of an oncogene amplified in a mouse tumor cell line." (PMID 20030851, 2009). "Supporting evidence for the hypothesis that MDM2 SNP309 influences tumor formation is derived from the clinical outcomes obtained from different research groups." (PMID 19144119, 2009). "Tumour cell positivity is characteristic for calponin, MDM-2 and PDGFRα." (PMID 19830228, 2009). "Inactivation of mdm2-induced G0/G1 arrest may contribute to tumor development, hence, mdm2 appears to play dual roles, as a tumor suppressor and as an oncogene, depending on the levels of mdm2 being expressed in the cell." (PMID 19445705, 2009). "Interruption of the role of p53s as a tumour suppressor by MDM2 may be one of the mechanisms by which cancer cells evade current therapy." (PMID 19707204, 2009). "The majority of studies have examined total MDM2 mRNA expression in normal and tumour tissues." (PMID 18781178, 2008). "MDM2 is amplified and/or overexpressed in a variety of human tumours of diverse tissue origins." (PMID 18781178, 2008).